CLDN9 (claudin 9)
Diseases named in the same sentence as CLDN9 in open-access papers (continued):
Sharing a sentence is not in itself a finding about the gene and the disease.
tumor (8 papers, 2018 to 2023). "On the contrary, levels of Cldn1,Cldn4,Cldn6,Cldn9,Cgn,F11r, and Cdh1, associated with exacerbated inflammation, perturbation of the TJ assembly, and even with mesenchymal transformation or tumour progression, were overexpressed." (PMID 37794493, 2023). "The analysis of the CLDN9 staining also indicated the pattern changing between normal tissues and tumor tissues." (PMID 38137355, 2023). "Another intriguing observation was the expression pattern of the CLDN9 mRNA and proteins in relation to tumor grade." (PMID 38137355, 2023). "Overexpression of CLDN9 could promote tumor cell invasion through Tyk2/STAT3 signaling." (PMID 35223866, 2021). "Significant differences in CLDN3, CLDN4, CLDN5, CLDN6, CLDN9, CLDN11, and CLDN12 expression were evident as a function of tumor stage." (PMID 35281827, 2022). "The results showed that CLDN9, AK4, PC, GPC1, and SRD5A3 were upregulated in EC tissues compared to in normal endometrium tissues, whereas B4GALT1, GMPPB, B4GALT4, and CHST6 were downregulated in tumor tissues." (PMID 31807118, 2019).
cancer (4 papers, 2020 to 2023). A tumor composed of atypical neoplastic, often pleomorphic cells that invade other tissues. "In Her-2-negative MCF7 and MDA-MB-231 cancer cells, loss of CLDN9 significantly increased sensitivity to several chemotherapeutic drugs including paclitaxel, gemcitabine and methotrexate, which was not seen in Her-2(+) SKBR3 cells." (PMID 38137355, 2023). "Relative PAM, STC1, and HDAC4 expression were down-regulated, whereas CASP6, CHST6, SLC16A3, TPI1, KDELR3, VCAN, and CLDN9 were highly expressed in carcinoma tissues compared to the para-carcinoma tissues." (PMID 33424916, 2020). "Tight junctions in cancer may also govern paracellular permeability and hence intratumor drug penetration; thus, CLDN9 proteins at the tight junctions in cancer cells may participate this restriction of intratumor availability in drugs." (PMID 38137355, 2023). "There are likely other mechanisms unrelated to tight junction that may operate here, including the possibility of the junctional role for CLDN9 in cancer cells themselves." (PMID 38137355, 2023). "Additionally, the Her-2 inhibitor and CLDN9 inhibition may have additive value in sensitizing cancer cells." (PMID 38137355, 2023). "CLDN9 is an HCC proto-oncogene that increases the invasiveness and migration capability of cancer cells by affecting the STAT3 signaling pathway." (PMID 33686959, 2021). "The overall survival of patients, based on the survival data from “The cancer genome Atlas (TCGA)” from the STAD study (TCGA Stomach Cancer), shows a significant positive effect (P=0.004) in those patients with a lower expression of Claudin-9." (PMID 39296813, 2021).
infection (4 papers, 2019 to 2023). The state of being infected such as from the introduction of a foreign agent such as serum, vaccine, antigenic substance or organism. "CLDN1, CLDN6, and CLDN9 usages on HCVpp infection were previously reported in other genotypes than genotype 2a, which HCV-JFH1 belongs to22,23." (PMID 36424447, 2022). "Baseline transcripts were present for several potential ZIKV receptors and claudin 9 mRNA was increased by infection." (PMID 31289325, 2019). "We found that GBVBpp could infect CLDN1 with EL1 replaced with that of CLDN9 (ChimB), but infection fell below the limit of detection when EL2 was swapped (ChimA), suggesting that the C-terminal region containing EL2 of CLDN1 is critical for GBV-B entry." (PMID 37310242, 2023). "Consistently, GBVBpp infection was observed when EL2 of CLDN1 was introduced into CLDN9 (ChimC)." (PMID 37310242, 2023). "Thus, CLDN6 is more likely than CLDN9 to contribute to M706L-carrying HCV-JFH1 infection in hepatic Huh7-derived cells." (PMID 36424447, 2022). "HCV H77pp infection of CLDN6- and CLDN9-transduced HEK293T cells confirmed that the ectopic protein was correctly folded and functional." (PMID 37310242, 2023). "Whereas HCV-JFH1-tau infection depends only on CLDN1, HCV-JFH1-tau/M706L infection exhibited the expanded receptor usage options: CLDN1, CLDN6, and CLDN9 proteins." (PMID 36424447, 2022). "Cldn1-specific neutralizing antibodies only partially inhibited infection of Huh7.5 cells by HCV strains with broad claudin tropisms, suggesting a possible escape from Cldn1-specific targeting molecules through Cldn6 or Cldn9 in cell culture." (PMID 31561440, 2019). "CLDN9 was up regulated in ZIKV-infected hSCs, but other junctional protein mRNAs were not affected by infection." (PMID 31289325, 2019).
CLDN9 also shares sentences with these, for which no sentence is quoted: acromegaly (1 paper); autosomal recessive deafness (1); Beaulieu-Boycott-Innes Syndrome (1); colon cancer (1); colorectal cancer (1); hyperglycaemia (1); Insulin resistance (1); metastasis (1); oesophageal cancer (1); parasite infections (1); prostate carcinoma (1); Stomach (1); uveal melanoma (1).